TMF1P1 (TATA element modulatory factor 1 pseudogene 1)
Gene: Processed pseudogene on chromosome 16 (13,458,326 to 13,458,698, forward strand). Ensembl gene ENSG00000262235.
Diseases named in the same sentence as TMF1P1 in open-access papers:
TMF1P1 is named in the same sentence as 1 disease in open-access papers, as found by Europe PMC text mining. Sharing a sentence is not in itself a finding about the gene and the disease. The quoted sentences say what the papers report.
glomerulonephritis (1 paper, 2024). A renal disorder characterized by damage in the glomeruli. "Meanwhile, several mapped genes of these GWAS significant SNPs were also found significant in IGA glomerulonephritis (e.g., DEFA9P and DEFA10P), neuropsychological conditions (e.g., TMF1P1), despite of reporting uncommon SNP." (PMID 39240858, 2024).